SOCS1 (suppressor of cytokine signaling 1)
Diseases named in the same sentence as SOCS1 in open-access papers (continued):
Sharing a sentence is not in itself a finding about the gene and the disease.
tumor (continued). "CUEDC2 regulates the phosphorylation of STAT3 by regulating the stabilization of the SOCS1 or SOCS3 protein in tumor cells." (PMID 32393737, 2020). "SOCS1 expression was comparable between tumor tissues and adjacent normal tissues in the TCGA-LIHC dataset, whereas SOCS3 expression was significantly reduced in tumor tissues." (PMID 32807134, 2020). "SOCS1 acts as anti-proliferative and increasing SOCS1 levels has proved its potential in reducing tumour size in proliferative cancers using in-vitro and in-vivo models." (PMID 32722523, 2020). "Taken together, these data indicate SOCS1 plays a role of tumor suppressor in NPC cells by directing the ubiquitin-proteasome-mediated degradation of STAT1 in the JAK/STAT signaling pathway." (PMID 32831137, 2020). "Not only are 16p13 abnormalities a novel association in dFL, we also found that the minimally altered region(s) encompassed CREBBP, CIITA, and SOCS1, which suggests a possible co-operative mechanism for tumor immune evasion." (PMID 32555149, 2020). "As expected, tumours derived from SOCS1-transfected SMMC-7721 cells presented decreased p21 and p27 expression compared tumours derived from control cells." (PMID 32096766, 2020). "Compared with the control tumours, tumours derived from cells with SOCS1 overexpression presented an apparent decrease in tumour size and weight." (PMID 32096766, 2020). "Given the tumor suppressor functions and overlapping mechanisms of action of SOCS1, SOCS3 and PIK3R1, further work is needed to disentangle the highly significant negative correlation between SOCS1/SOCS3 and PIK3R1." (PMID 32807134, 2020). "Calcitriol or its analogues downregulated the expression of 4 genes related to the Th1 response in tumour tissue (Ifng (only calcitriol), Socs1, Tbx21 and Fasl) and upregulated 5 genes related to the Th2 response (Ccl11, Ptgdr2, Il9, Asb2 and Il5)." (PMID 31595196, 2019). "In a phase I clinical trial, the human DCs derived from peripheral blood mononuclear cells were delivered with human SOCS1 shRNA and tumor antigens via an adenovirus vector." (PMID 30658461, 2019). "SOCS1 and SOCS3 have been associated with tumour progression and response to treatments in different kinds of cancers, including GBM." (PMID 30811476, 2019). "MiR-122 was found to prevent the influence of the tumor-derived condition medium on MC activation by targeting SOCS1." (PMID 31052286, 2019). "Adjacent non-tumor tissue samples as well as 31 paired ATC were tested by western blot for the purpose of determining the expression of SOCS1 in ATCs." (PMID 31718618, 2019). "SOCS1, on the other hand, is known to act as a tumor suppressor in various cancers as well as a potent inhibitor of inflammation." (PMID 31137686, 2019). "Suppressor of cytokine signaling-1 (SOCS1), is a tumour suppressor gene and suppresses cytokine signaling and degrades HPV E7 protein." (PMID 31766427, 2019). "In another study, SOCS1 was seen to exert its tumor suppressor activity in colorectal cancer cells by reducing tumor cell invasion and inhibiting EMT." (PMID 30959836, 2019). "The ex vivo delivery of SOCS1 siRNA to BMDCs via octa-arginine (R8)-modified lipid envelope-type nanoparticles effectively delayed tumor growth." (PMID 30658461, 2019). "For example, the methylation of the suppressor of cytokine signaling 1 (SOCS1), a negative regulator of the JAK/STAT pathway regarded as a tumor suppressor gene, was found to be positively associated with HCV infection status." (PMID 30917875, 2019).
tumor (continued). "Tumor tissue lysates from CT26 cells that received exosomes from the CT26Flag−CAGE1 cells displayed increased FcεRIβ expression, and interactions of FcεRIβ with SOCS1 and Lyn compared to the tumor tissue lysates of CT26 cells that received CT26 exosomes." (PMID 31799196, 2019). "We observed upregulations of immune checkpoint molecules IL-10, PD1, TGF-β and inflammatory molecule IFN-γ in tumor tissue while SOCS1 and SOCS3 expressions were found to be comparable to controls." (PMID 30859089, 2019). "Consistent with a possible SOCS1 tumour-promoting role, colon carcinogenesis induced by 1,2-dimethylhydrazine plus dextran sulphate sodium was reduced in Socs1−/− mice." (PMID 31091767, 2019). "We also found abolished expression of the suppressor of cytokine signaling 1 (SOCS1) in DFTD tumor cells, a known inhibitor of STAT3 activation." (PMID 30645971, 2019). "In situ hybridization also confirmed overexpression of SOCS1–3 transcripts in both tumor tissue and reactive stroma." (PMID 30453988, 2018). "The adenovirus (Ad-siSSF) delivers two tumor-associated antigens (TAAs), survivin and MUC1; secretory bacterial flagellin for DC maturation; and an RNA interference moiety to suppress SOCS1." (PMID 29415891, 2018). "Vaccination with HPV16mE7 pulsed, shRNA-mediated SOCS1-silenced DCs showed significantly improved anti-tumor effects compared to non-SOCS1-silenced controls in vitro and in vivo." (PMID 29867960, 2018). "Mechanistically, upregulation of miR-155 and downregulation of suppressor of cytokine signaling-1 (SOCS1) were confirmed as a target signaling pathway to positively regulate the anti-tumor response of CD8+ T cells." (PMID 30619765, 2018). "In prior mouse tumor model studies, we demonstrated that SOCS1 shRNA-silenced DCs stimulated with TLR agonists, including LPS and polyinosinic/polycytidylic acid, were able to persistently induce CTLs, which resulted in effective antitumor responses." (PMID 29415891, 2018). "SOCS-1, SOCS-3 inhibiting JAKs and regulating tumor-associated inflammation, then inhibit a variety of tumor development and invasion." (PMID 30788302, 2018). "In particular, SOCS1 is thought to act as a pivotal tumor suppressor through negative regulation of JAKs and plays vital roles in tumor progression." (PMID 30450337, 2018). "Suppressor of cytokine signaling 1 (SOCS1) is typically perceived as a tumor suppressor, and silencing of the SOCS1 gene by hypermethylation in its promoter region is frequent in many types of cancer." (PMID 30584449, 2018). "In this study, we found that miR-221-5p can specific target SOCS1, which is tumor suppressor genes,and suppress SOCS1 protein expression in PC3 and DU145 cells." (PMID 29506516, 2018). "Suppressor of cytokine signaling 1 (SOCS1) is considered a tumor suppressor due to frequent epigenetic and micro-RNA-mediated repression of its gene expression in diverse cancers." (PMID 28235401, 2017). "Consistently, PROS reduced the expression of p-Src, p-AKT, cyclooxygenase 2 (COX-2) as survival genes and suppressor of cytokine signaling 1 (SOCS-1) that promotes tumor progression and toll like receptor (TLR) signaling, but not SHP-1, in A549 and H460 cells." (PMID 29254203, 2017). "Down-regulation of SOCS1 decreased β-hexosaminidase activity while increasing the expression of miR-122 in tumor tissue." (PMID 28968979, 2017). "SOCS1peptide prevented antigen from increasing β-hexosaminidase activity in tumor tissue and prevented antigen from increasing the expression of SOCS1 and HDAC3 in tumor tissue." (PMID 28968979, 2017). "In fact, elevated miR-30d expression in PCa specimens correlates with early biochemical recurrence, supporting a tumor suppressor role for SOCS1 in PCa." (PMID 28235401, 2017).
tumor (continued). "SOCS1 can mediate tumor suppression by several potential mechanisms that were defined using cell and animal models." (PMID 28235401, 2017). "SOCS1 displays a potent antiproliferative effect on tumor cells and is dependent on the inhibition of STAT3 and on other signaling proteins." (PMID 28228755, 2017). "While the SOCS1 function in carcinogenesis among different cancer cells is still controversial, it has been suggested that modulation of SOCS1 expression in tumor cells for antitumor therapy is highly context-dependent." (PMID 29268708, 2017). "Taken together, SOCS1 shows an antitumor effect in most of tumors through inhibiting tumor proliferation, attenuating tumor invasion, and reducing the sensitivity of tumor cells to cytokines or hormones." (PMID 28228755, 2017). "SOCS1 methylation was identified in 105 (42.7%) of the tumor tissues and the number for SOCS3 methylation status are164 (66.7%)." (PMID 28404963, 2017). "SOCS-1 is classically described as a tumor suppressor in many cancers, including hematopoietic malignancies." (PMID 28369102, 2017). "Based on the phenotype of SOCS1-silenced B16F10-Nex2 cells the present work focused on the expression of proteins relevant to tumor development and the signaling pathways related with SOCS1." (PMID 28079159, 2017). "The present work aimed at analyzing the SOCS1 cell signaling and expression of proteins relevant to tumor development." (PMID 28079159, 2017). "Small molecules that mimic the physiological action of the KIR domain of SOCS1 have been designed, and were shown to ameliorate inflammatory processes by down-regulating specific immune and pro-tumor responses both in vivo and in vitro." (PMID 28445952, 2017). "A SOCS1 suppressor antagonist enhances antigen-presenting capacity and tumor cell antigen-specific cytotoxic T lymphocyte responses." (PMID 29268708, 2017). "Down-regulation of SOCS1 decreased the expression of HDAC3, TGaseII and COX-2 and inhibited the interactions of FcεRIβ with Lyn, HDAC3 and SOCS1 in tumor tissue." (PMID 28968979, 2017). "In order to evaluate the protein expression of SOCS1 and its putative downstream targets of tumor suppression in PCa, we constructed TMAs from archived PCa specimens and performed automated IHC staining to ensure staining homogeneity." (PMID 28235401, 2017). "As we have shown, SOCS1 can act as both a tumor suppressor and an oncogene in BCR-ABL mediated transformation." (PMID 28753604, 2017). "PD-L1 expressing cells, in the SOCS1-neg prophylactic cell treatment, were significantly reduced in lung tissue colonized with tumor cells." (PMID 28079159, 2017). "Even though the loss of SOCS1 did not correlate with increased MET or p21 expression as we had expected, our findings support the tumor suppressor function of SOCS1, and the oncogenic potential of MET and p21 in PCa." (PMID 28235401, 2017). "Silencing of tumor-related genes and tumor-suppressor genes such as SOCS1, hMLH1, and RASSF1A is achieved by hypermethylation of CpG islands in promoter sequences that downregulates mRNA transcript expression." (PMID 28401148, 2017). "In fact, both pro-apoptotic and anti-apoptotic functions of SOCS1 have been noted depending on the tumor cell types and apoptotic triggers." (PMID 27613835, 2016). "In order to investigate the role of SOCS1 in tumor cell response to ROS, induction of SOCS1 expression by hydrogen peroxide, a direct source of ROS, was first examined." (PMID 27613835, 2016).
tumor (continued). "Such tumor suppressive functions of SOCS1 through the activation of cellular anti-oxidant defense system would be particularly useful in control of colon cancers surviving high oxidative stress induced upon chemo- or radiation therapy." (PMID 27613835, 2016). "Because multiple factors involved in EMT are correlated with invasive property of tumor cells, we have examined the effect of SOCS1 in invasion capacity of HCT116 cells and the role of ROS in this process." (PMID 27613835, 2016). "Significantly, SOCS1 knockdown performed on indolent phase MAC-1 cells induced inflammatory Th17-related cytokines seen at tumor progression, thus mimicking the effects of exogenous IL-2." (PMID 27144517, 2016). "In this study, we examined methylation patterns of ten tumor-associated genes (RASSF1A, GSTP1, RIZ1, SOCS1, TNFRSF10C, hTERT, NRG1, CLU, miR-203, miR-663) and of the LINE-1 repetitive element in 45 HCC and 17 matching non-tumor livers." (PMID 25889455, 2015). "This goes hand-in-hand with increased levels of cleaved caspase-3 and high SOCS1 in these tumours, which leads to suppression of STAT3 signalling." (PMID 25820993, 2015). "The suppressor of cytokine signaling 1 (SOCS1) and cyclin-dependent kinase inhibitor 1A (p21KIP) are known to regulate tumor cell proliferation." (PMID 25893382, 2015). "The methylation of the SOCS-1 gene was shown to be associated with the reduced expression of the SOCS gene, LN metastases and an advanced tumor stage." (PMID 25997695, 2015). "To study more closely the mechanism by which anti-miR-155 mimetics reduce tumour growth, we assessed expression of miR-155 and its targets, C/EBPβ and SOCS1, in the murine tumours." (PMID 25820993, 2015). "They nucleofected DCs with a plasmid that encoded an shRNA to SOCS1; overexpressed MAGE3, a tumor antigen; and overexpressed HMGB1 to stimulate NF-κB signaling." (PMID 26579124, 2015). "While the specific pathobiological role in lymphomagenesis remains to be elucidated, SOCS1 is a postulated tumor suppressor gene, that is frequently targeted by somatic hypermutation and inactivated by genomic mutations." (PMID 26336985, 2015). "Previous studies have shown that SOCS1 is induced in DCs and silencing of SOCS1 enhances antigen presentation by DCs and antigen-specific anti-tumor immunity." (PMID 24826993, 2014). "Current research demonstrates a significant role for SOCS1 as a tumour suppressor both in haematological and solid tumours." (PMID 24757565, 2014). "The expression of SOCS1 gene is often silenced in these tumours by hypermethylation of CpG islands of the SOCS1 promoter." (PMID 24757565, 2014). "In human tumors, SOCS3 expression identifies macrophages with enhanced tumor killing, whereas SOCS1 expressing macrophages (M2) favor tumor survival." (PMID 25120543, 2014). "Although the specific role in lymphomagenesis remains to be elucidated, SOCS1 is a postulated tumor suppressor gene that is frequently inactivated by genomic mutations." (PMID 23296022, 2013). "The values of SOCS1 protein were 26.49±14.21 in tumor specimens, and 58.40±18.13 in control mucosa specimens." (PMID 23437123, 2013). "In mice fed with WD, proximal colon mucosa, the predominant site of cancer formation in LS, exhibited a significant expression decrease in tumor suppressor genes, Dkk1, Hoxd1, Slc5a8, and Socs1, the latter two only in the Mlh1+/- mice." (PMID 24204690, 2013). "The protein levels of SOCS1 in control mucosa tissues were 2.2-fold higher than those in tumor tissues; the differences were statistically significant (p<0.001)." (PMID 23437123, 2013). "Four out of six neoplasias were found in the mice showing higher methylation at CGIs of all five genes Dkk1, Slc5a8, Hoxd1, Socs1 and Sfrp1 (B219, B220), of the four genes Dkk1, Hoxd1, Socs1 and Sfrp1 (B215), or of Dkk1 (B236)." (PMID 24204690, 2013). "The SOCS1 protein expression difference between 21 pairwised tumor and control mucosa specimens was statistically significant (T = -8.892, P<0.001)." (PMID 23437123, 2013).
tumor (continued). "In contrast, SOCS1 acts as an oncogene by inhibiting the IFN-у mediated effects on cancer cells such as enhanced anti-tumor immunity, cell cycle arrest, apoptosis and reduced angiogenesis." (PMID 24058673, 2013). "SOCS1 protein expression was also compared between 21 pairwised tumor and control mucosa specimens obtained from 21 patients who received total laryngectomy." (PMID 23437123, 2013). "Immunohistochemical staining of human BCC paraffin sections showed strong and specific staining of SOCS1 protein throughout the tumor islands and in some infiltrated areas of the surrounding stroma thus supporting qRT-PCR data (left)." (PMID 24058673, 2013). "The roles of SOCS1 in tumorigenesis are diverse and strongly depend on the origin or type of the tumor." (PMID 24058673, 2013). "We observed a reduction in the number and size of colonies in the presence of shRNA directed against SOCS1 compared to control shRNA, indicating that high levels of SOCS1 expression promote tumor growth." (PMID 24058673, 2013). "These included increased expression of known proto-oncogenes, such as Kras and Rras, and the oncomiR microRNA-155, as well as suppression of the expression of Socs1, a known tumor suppressor." (PMID 23496831, 2013). "Having shown that high levels of Hh signaling impairs IFN-y signaling by SOCS1 activation, we explored the influence of SOCS1 on Hh driven tumor growth." (PMID 24058673, 2013). "Histopathologic analysis of the tumor xenografts demonstrated significantly intense SOCS1 staining and less proliferative features in the anti-miR-30d xenografts compared with the control tumors." (PMID 23231923, 2012). "The expression of SOCS1 is decreased in many human cancers including PCa, suggesting the role of SOCS1 as a tumor suppressor." (PMID 23231923, 2012). "Immunohistochemical staining of SOCS1 in PCa tissues demonstrated that SOCS1 expression in tumor areas was very weak in most cases, whereas strong staining was observed in the adjacent normal prostate tissues (P < 0.001)." (PMID 23231923, 2012). "Both C/EBP-β and SOCS1 are tumor suppressors and often downregulated in hepatocellular carcinomas and hepatoblastomas." (PMID 22518321, 2012). "The complexes silenced suppressor of cytokine signaling 1 (SOCS1) expression and retarded the growth of B16 tumor in mice." (PMID 21995320, 2011). "The DFS and OS curves for women with tumours which were classified as having 'high levels' of SOCS1 transcripts were found to differ significantly from those of their 'low level' counterparts." (PMID 20433750, 2010). "It is currentlythought that SOCS1 contributes to tumor suppression due to its ability tocontrol and terminate the activation of STATs." (PMID 20622265, 2010). "Taken together, these data suggest that SOCS-1 functions as a tumour suppressor in the JAK/STAT pathway." (PMID 15354212, 2004). "In normal breast tissue obtained at a distance from the tumour, the macroautoradiographic hybridisation signal for SOCS-1–3 and CIS mRNA was observed in regions corresponding to epithelial component of the duct." (PMID 12888825, 2003). "On the pathologic sections, we consistently observed that SOCS-1–3 and CIS gene expression was strongly associated with the tumor cells and was significantly higher than the basal level in normal adjacent epithelial and connective tissues (P<0.05)." (PMID 12888825, 2003). "Interestingly, HeLa cells exposed to 20 μM capsaicin for a long time showed reversed hypermethylation of CADM1 and SOCS1, restoring the expression of these tumor suppressors." (PMID 40510497, 2025). "Moreover, in OLP, upregulated miR-155, targets the miR-155/SOCS1 axis, a pathway with high involvement in immune system and in macrophage differentiation, functioning overall as a tumor-promoting factor." (PMID 41303164, 2025).